DNMT1 (DNA methyltransferase 1)
Description:
DNA methyltransferase that methylates CpG residues. Preferentially methylates hemimethylated DNA. Associates with DNA replication sites in S phase maintaining the methylation pattern in the newly synthesized strand, that is essential for epigenetic inheritance. Associates with chromatin during G2 and M phases to maintain DNA methylation independently of replication. It is responsible for maintaining methylation patterns established in development. DNA methylation is coordinated with methylation of histones. Mediates transcriptional repression by direct binding to HDAC2. In association with DNMT3B and via the recruitment of CTCFL/BORIS, involved in activation of BAG1 gene expression by modulating dimethylation of promoter histone H3 at H3K4 and H3K9. Probably forms a corepressor complex required for activated KRAS-mediated promoter hypermethylation and transcriptional silencing of tumor suppressor genes (TSGs) or other tumor-related genes in colorectal cancer (CRC) cells. Also required to maintain a transcriptionally repressive state of genes in undifferentiated embryonic stem cells (ESCs). Associates at promoter regions of tumor suppressor genes (TSGs) leading to their gene silencing.
Synonyms: M.HsaI; AIM; CXXC9; DNMT; MCMT; ADCADN; HSN1E
Tractability: Small molecule: an approved drug acts on it; a structure with a bound ligand is known; a high-quality ligand is known; it has a high-quality binding pocket; it belongs to a druggable protein family. PROTAC: UniProt records ubiquitination sites on it; ubiquitination databases record sites on it; its protein half-life has been measured; a small molecule that binds it is known.
Target class: DNA methyltransferase; Epigenetic regulator; Writer
Chemical probes: DECITABINE, GSK3484862 (high quality), PD134440, PD134441
Gene: Protein-coding gene on chromosome 19 (10,133,342 to 10,231,286, reverse strand). Ensembl gene ENSG00000130816.
Subcellular location: Nucleus; Chromosome
Subcellular location (Human Protein Atlas): Nucleoplasm
Pathways (Reactome):
Gene expression (Transcription): DNA methylation; NoRC negatively regulates rRNA expression; PRC2 methylates histones and DNA
Disease: Defective pyroptosis; Nuclear events stimulated by ALK signaling in cancer
Metabolism of proteins: SUMOylation of DNA methylation proteins
Signal Transduction: STAT3 nuclear events downstream of ALK signaling
Gene Ontology:
Molecular function: DNA (cytosine-5-)-methyltransferase activity; DNA binding; DNA-methyltransferase activity; histone H3K14ub reader activity; histone H3K18ub reader activity; histone H3K23ub reader activity; promoter-specific chromatin binding; protein binding; chromatin binding; lncRNA binding; methyl-CpG binding; methyltransferase activity; RNA binding; zinc ion binding
Biological process: chromosomal DNA methylation maintenance following DNA replication; negative regulation of gene expression; negative regulation of gene expression via chromosomal CpG island methylation; negative regulation of phenotypic switching; negative regulation of vascular associated smooth muscle cell apoptotic process; negative regulation of vascular associated smooth muscle cell differentiation; positive regulation of gene expression; positive regulation of vascular associated smooth muscle cell proliferation; negative regulation of transcription by RNA polymerase II; DNA methylation-dependent constitutive heterochromatin formation
Cellular component: chromosome; heterochromatin; mitochondrion; nucleoplasm; nucleus; pericentric heterochromatin; replication fork
Genetic constraint (gnomAD): Loss-of-function variants: 22 observed, 208.83 expected, observed/expected ratio (o/e) 0.11, 90% interval 0.074 to 0.15. The upper end of that interval is the gene's LOEUF score, 0.15, which puts it in group 1 of 6, group 1 being the genes least tolerant of losing a copy. Missense variants: 1,275 observed, 2,223.4 expected, observed/expected ratio (o/e) 0.57, 90% interval 0.55 to 0.6. Synonymous variants: 808 observed, 861.6 expected, observed/expected ratio (o/e) 0.94, 90% interval 0.88 to 0.99.
Gene-disease validity (ClinGen):
ClinGen rates the evidence that DNMT1 causes each of these diseases.
autosomal dominant cerebellar ataxia, deafness and narcolepsy (autosomal dominant): Definitive. Autosomal dominant cerebellar ataxia, deafness and narcolepsy (ADCA-DN) is a polymorphic disorder and a subtype of autosomal dominant cerebellar ataxia type 1 (ADCA type 1) characterized by ataxia, sensorineural deafness and narcolepsy with cataplexy and dementia.
Homologues: Orthologues: chimpanzee DNMT1 (99% identical), macaque DNMT1 (98% identical), dog DNMT1 (90% identical), pig DNMT1 (88% identical), guinea pig DNMT1 (79% identical), rat Dnmt1 (77% identical), mouse Dnmt1 (77% identical), tropical clawed frog dnmt1 (68% identical), zebrafish dnmt1 (64% identical). Paralogues in human: TRDMT1 (6% identical).
Diseases named in the same sentence as DNMT1 in open-access papers:
DNMT1 is named in the same sentence as 512 diseases in open-access papers, as found by Europe PMC text mining. Sharing a sentence is not in itself a finding about the gene and the disease. The quoted sentences say what the papers report.
breast cancer (368 papers, 2004 to 2026). A primary or metastatic malignant neoplasm involving the breast. "While the role of DNMT1 in breast cancer brain metastasis has been established, its underlying molecular mechanism remains to be fully elucidated." (PMID 41381440, 2025). "This approach not only revealed candidate genes directly influenced by DNMT1-mediated methylation but also provided broader insights into DNA methylation events associated with breast cancer brain metastases." (PMID 41381440, 2025). "Elevated DNMT1 expression in breast cancer has been linked to increased tumor aggressiveness and metastatic capacity." (PMID 41381440, 2025). "For instance, SNP rs16999593, which produces missense substitution H97R in DNMT1, is associated with a high risk of breast cancer." (PMID 39334883, 2024). "Changes in DNA methylation associated with DNMT1 were also observed in breast cancer cells treated with tamoxifen." (PMID 39201247, 2024). "Results showed that the A allele of DNMT1 rs2228611 decreased the risk of overall breast cancer (OR = 0.74; 95%CI = 0.56–0.97; p = 0.03; GA + AA vs. GG)." (PMID 39125744, 2024). "DNMT1 has been genetically reported to associate with a number of diseases, including coronary artery disease, and gastric and breast cancers." (PMID 36950137, 2023). "Reduced reelin expression is associated with increased DNMT-1 in gastric and breast cancers, and a gradual increase in DNMT-1 mRNA abundance from ulcerative colitis to colitis-associated colorectal tumors has been reported." (PMID 36290310, 2022). "Further research has been performed and found that poor breast cancer survival was associated with the overexpression of DNMT1, which is commonly observed in TNBC." (PMID 35838271, 2022). "In TNBC, distinct DNA methylation profiles have been observed compared to other breast cancer subtypes; altered DNA methylation was shown to be associated with the oncogenic role of DNMT1." (PMID 35158742, 2022). "Collectively, this study reveals the underlined epigenetic events responsible for RUNX3-implicated breast cancer metastasis along with the classification of DNMT1 modulators that can potentially drive the perception of epigenetic-based tumor therapy." (PMID 35898303, 2022). "The amount of DNMT1 also increased in mammary tumors and CSCs and aberrant DNA methylation caused resistance to treatment in CSCs by regulating proteins involved in cell growth." (PMID 34051847, 2021). "Overexpression of DNMT1 contributes to gene promoter hypermethylation and is associated with the malignant potential and poor prognosis of breast cancer." (PMID 34950205, 2021). "Previous studies have shown that genetic alterations in DNMT1 associated with a low risk of developing breast cancer in the European Caucasian population and that DNMT1 expression was higher in Caucasians than in Asians and African-Americans33." (PMID 33500531, 2021). "In order to find out the possible reason underlying hypermethylation of KLF4 promoter in breast cancer, we detected the expression of DNMT1 in these 50 breast carcinoma and adjacent normal tissues by IHC analysis." (PMID 34150611, 2021). "One of the leading causes of breast cancer is an increase in DNMT1 activity, which leads to the alteration in DNA methylation patterns and the increase in DNA methylation in CpG islands." (PMID 33450856, 2021). "In breast cancer, high DNMT1 expression is significantly associated with poor survival (p < 0.05) using multivariate analysis." (PMID 34572918, 2021). "Further studies of the effects of DNMT1 polymorphisms on specific breast cancer types are still needed." (PMID 28473984, 2017). "Our previous study showed that CLDN6 silencing in breast cancer cells was associated with DNMT1 mediated DNA methylation." (PMID 28867761, 2017).
breast cancer (continued). "To date, BRCA mutations are the only known cause of hereditary breast cancer, and DNA methylation is among the most well-studied epigenetic modifications, which is maintained by the enzyme DNA methyltransferase 1 (DNMT1)." (PMID 24502362, 2014). "This study provides new insights into the causes and prognosis of DNMT1 inactivation in BRCA1-mutated breast cancer." (PMID 24502362, 2014). "Based on the results above, we next explored the relationship between E2F1 motif methylation and DNMT1 expression in a large number of BRCA1-mutated breast cancer specimens." (PMID 24502362, 2014). "Hypermethylated E2F transcription factor 1 (E2F1) motif is a key regulatory element for the DNMT1 gene in BRCA1-mutated breast cancer." (PMID 24502362, 2014). "After the deletion of H3K9ac and/or E2F1 enrichment in BRCA1-mutated breast cancer, the transcription of DNMT1 was significantly down-regulated." (PMID 24502362, 2014). "We conclude that women with the DNMT1 SNP (A201G, rs2228612) GG homozygous genotype (variant) have a lower risk of developing breast cancer compared to heterozygous or wildtype genotypes." (PMID 23638630, 2013). "In this study, we were able to show a significant association between the DNMT1 gene polymorphism (A201G, rs2228612) and the risk of breast cancer in the female Caucasian population." (PMID 23638630, 2013). "In relation to breast cancer risk, DNMT1 gene polymorphisms have been solely reported in association with sporadic infiltrating ductal breast cancer among Chinese women." (PMID 23638630, 2013). "ChIP assays revealed that DNMT1 protein is associated with the silenced ERα promoter in MDA-MB-231 breast cancer cells, whereas the active ERα promoter in MCF-7 cells shows little association of DNMT1 protein (Figure." (PMID 22558281, 2012). "High expression of DNMT1 is associated with poor breast cancer survival and progression of disease." (PMID 40299558, 2025). "We believe that the development of DIVA represents an important step toward establishing a meaningful early diagnostic test for breast cancer, and that plasma DNMT1 activity shows promise as a biomarker for both tumor burden assessment and treatment monitoring in clinical perspective." (PMID 40317882, 2025). "Future studies incorporating breast cancer brain metastasis cohorts with comprehensive follow-up data are warranted to validate the association of DNMT1/RASSF1A expression and methylation status with patient outcomes, thereby strengthening the translational relevance of our findings." (PMID 41381440, 2025). "Abnormal DNA methylation is also associated with drug resistance in breast cancer cells, indicating that DNMT1 overexpression could also be a cause of BC resistance to therapy." (PMID 38257347, 2024). "The TQ-mediated inhibitory effects on MCF7 and T47D cells were associated with the downregulation of DNMT1, indicating that TQ could be a promising candidat for the treatment of breast cancer by inhibiting DNMT1." (PMID 38257347, 2024). "Moreover, we revealed that tumour-associated macrophages (TAMs) increase DNMT1 expression in breast cancer cells via the IL-6-pSTAT3-ZEB1-DNMT1 axis in the tumour microenvironment." (PMID 36273188, 2022). "Furthermore, multivariate Cox regression analysis was conducted to investigate the link between the prognostic power of DNMT1 expression level and other well-known breast cancer risk factors." (PMID 35719957, 2022). "However, despite the evident role of RUNX3 in breast cancer and the relation of DNMT1 with RUNX3 gene, no study has explored the underlying epigenetic molecular events by which DNMT1 silences RUNX3 to promote breast cancer metastasis." (PMID 35898303, 2022).
breast cancer (continued). "However, we found that knockdown of DNMT1, but not DNMT3a and DNMT3b, resulted in restoration of FOXO3a expression, indicating that the downregulation of FOXO3a is associated with DNMT1-mediated hypermethylation of its promoter in breast cancer." (PMID 31296961, 2020). "In this study, we found an association between the DNMT1 rs2162560 SNP and self-perceived cognitive impairment in breast cancer patients; carriers of the A allele experienced lower odds of self-reported cognitive decline in two cognitive domains: concentration and functional interference." (PMID 31601979, 2019). "In breast carcinoma, chronic intermittent exposure to adriamycin induced hypermethylation that was associated with multidrug resistant phenotype in correlation to an upregulation of DNMT1, DNMT3A and DNMT3B and an increase in DNA methyltransferase activity." (PMID 31022903, 2019). "The meta-analysis also suggested that DNMT1 rs16999593 (T/C) may be associated with gastric cancer, while rs2228611 (G/A) may be associated with breast cancer." (PMID 28473984, 2017). "In MCF-7 breast cancer cells, the elevated DNMT1 protein is caused by its abnormal stability." (PMID 27525019, 2016). "Agoston suggested that the cause of the elevated DNMT1 protein levels could be attributed to an increase in protein half-life in breast cancer." (PMID 24502362, 2014). "Notably, only in BRCA1-mutated breast cancer cells was the E2F1 motif found to be the critical element for DNMT1 transcription (Figure3Bii)." (PMID 24502362, 2014). "Accordingly, specific regulatory mechanisms may exist, and DNMT1 expression is likely to be the result of a complex interaction of multiple factors in BRCA1-mutated breast cancer cells." (PMID 24502362, 2014). "Therefore, our results show that the DNMT1 gene polymorphism (A201G, rs2228612) with the g-allele (variant) is associated with a reduced risk of developing breast cancer." (PMID 23638630, 2013). "In the study presented herein, we identified one DNMT1 SNP (A201G, rs2228612) which could be relevant as a risk of developing breast cancer in the female Caucasian population." (PMID 23638630, 2013). "Moreover, the extracted information shows that aberrant expression of DNMT1 (DNA methyltransferase 1) breast cancer is associated with the loss of DNA methylation." (PMID 22168213, 2011). "Similarly, previous reports have showed that E2F1 could bind to the promoter of DNMT1 (encoding a DNA methyltransferase), and upregulate DNMT1 expression resulting in breast cancer cell proliferation." (PMID 39957240, 2025). "Interestingly, expression of DNMT1 is associated with poor survival in breast cancer, is overexpressed specifically within TNBC, induces cancer cell invasion and survival through hypermethylation of key tumor suppressors, and is considered an epigenetic target for therapeutic blocking." (PMID 37732899, 2023). "Furthermore, we examined whether the levels of FOXO3a, FOXM1, SOX2, and DNMT1 were associated with the survival of patients with breast cancer." (PMID 31296961, 2020). "METHODS: This nested case‒control study, conducted within the Arkansas Rural Community Health study (ARCH) cohort, examined the associations between polymorphisms in DNMT1, DNMT3A, and DNMT3B and breast cancer risk." (PMID 41663987, 2026). "We also observed an obvious and significant overexpression of DNMT1 in breast cancer tissue (score, 0.96; IQR, 0.34 – 1.54; p < 0.0001) compared to the adjacent tissues." (PMID 40317882, 2025). "On the other hand, a correlation was observed between higher DNMT1 expression and Ki-67 levels and higher histological grade in breast cancer, which partially supports our observation DNA hypermethylation." (PMID 40149562, 2025). "Using single-cell transcriptome sequencing of CTCs derived from in situ breast cancer models, DNMT1 was identified as a key promoter of tumor cell viability, migration, and invasion." (PMID 41381440, 2025).